TMPRSS2 (transmembrane serine protease 2)
Diseases named in the same sentence as TMPRSS2 in open-access papers (continued):
Sharing a sentence is not in itself a finding about the gene and the disease.
tumor (continued). "The interplay between TMPRSS2:ERG fusion (often represented by ERG expression) and PTEN loss allows for the classification of PCa into molecular subtypes providing critical insights into tumour biology." (PMID 40165885, 2025). "Furthermore, the dual role of TMPRSS2 as both a facilitator of viral entry and a tumor suppressor necessitates careful consideration when developing therapeutic interventions." (PMID 40145441, 2025). "Their research showed that TMPRSS2 expression is significantly reduced in numerous tumor tissues." (PMID 40145441, 2025). "Therefore, ACE2 and TMPRSS2 can provide new therapeutic targets and therapeutic strategies for tumor therapy during the novel coronavirus epidemic." (PMID 40145441, 2025). "FISH performed on PDX tumor material could confirm the presence of the TMPRSS2: ERG rearrangement, reassuring the final diagnosis of PCa metastases." (PMID 38907236, 2024). "Also, TMPRSS2-ERG fusion together with the loss of the tumor suppressor Phosphatase and Tensin homolog (PTEN) cooperates with the initiation of neoplasia." (PMID 38674385, 2024). "Accordingly, we color-coded each tumor sample by its TMPRSS2–ERG fusion status (164 tumor samples had unknown status)." (PMID 39347576, 2024). "TMPRSS2-ERG expression is detected during tumor initiation/progression in 50–60% of PCa." (PMID 37370750, 2023). "Furthermore, we examined the correlation between TMPRSS2 and the level of TILs infiltration in tumor and normal tissue respectively." (PMID 36992839, 2023). "Further research is needed to determine whether TMPRSS2 is crucial in mediating immune cells recruitment and remodeling the tumor microenvironment." (PMID 36992839, 2023). "M2 macrophages are tumor-promoting cells and TMPRSS2 was significantly associated with M2 in the tumor tissue of LUSC rather than in LUAD." (PMID 36992839, 2023). "Furthermore, in order to assess TMPRSS2 expression levels across tissues, we analyzed the expression of TMPRSS2 in the tumor and adjacent normal tissues based on the RNA-seq data of the various malignancies in the TCGA database." (PMID 35558557, 2022). "Additionally, we also analyzed the relationship between TMPRSS2 and immune cells in the tumor microenvironment." (PMID 35558557, 2022). "Furthermore, overexpression of ETV5 has been correlated with higher malignancy in multiple human tumour types including PCa, where it is present in a fusion with the TMPRSS2 gene." (PMID 35472129, 2022). "Besides its role in COVID‐19, TMPRSS2 considerably contributes to several physiological and pathological processes, included in tumour biology." (PMID 34951103, 2022). "TMPRSS2 is one of the androgen regulatory genes, participating in tumor invasion and metastasis." (PMID 35860569, 2022). "ACE2 and TMPRSS2 mRNAs were also detected in 47 non-tumor livers in the TCGA dataset." (PMID 35115564, 2022). "High expression of JUP was associated with adverse tumor stage, high Gleason grade lymph node metastases in a subset of PCa patients without TMPRSS2:ERG fusion." (PMID 36387263, 2022). "Growing evidence has shown that Transmembrane Serine Protease 2 (TMPRSS2) not only contributes to the severe acute respiratory syndrome coronavirus 2 (SARS‐CoV‐2) infection, but is also closely associated with the incidence and progression of tumours." (PMID 34951103, 2022). "This is consistent with the emerging view that metastasis and primary tumor growth are controlled by different factors and suggests that TMPRSS2 may be essential for tumor metastasis behavior." (PMID 35281819, 2022). "Expression of ACE-2 and TMPRSS2 in tumor cells may be remarkably different from normal tissue cells." (PMID 34399734, 2021).
tumor (continued). "In addition, TMPRSS2 protein levels were lower in tumor tissue compared to in the control tissue, while DNA methylation levels were dramatically higher in tumor samples for KIRC and KIRP." (PMID 34131396, 2021). "Over-expression of ACE-2 and TMPRSS2 in tumor tissues may render them more vulnerable to SARS-CoV-2 infection." (PMID 34399734, 2021). "Gene expression profile for TMPRSS2 in 32 different tumour tissues and their corresponding normal tissues (TCGA normal and GTEx data) revealed six significantly up‐regulated (in red colours) and six down‐regulated (in green colours) in different types of adenocarcinomas." (PMID 33609069, 2021). "Moreover, the DNA methylation levels of the ACE2 promoter in KIRC and KIRP were significantly downregulated in tumor tissue compared to in normal tissue, whereas TMPRSS2 expression was low in both KIRC and KIRP." (PMID 34131396, 2021). "Thus, it becomes clear that the status of TMPRSS2 fusion results in methylation differences between different tumor types." (PMID 33963293, 2021). "The expression of TMPRSS2–ERG transcript was detected in 50% (36/72) of PCa tumor samples." (PMID 34205581, 2021). "Mechanistically, downregulation of TMPRSS2 significantly correlated with aberrant upregulation of specific microRNAs, which might target TMPRSS2 post-transcriptionally, thereby leading to its reduced expression levels in tumor tissues." (PMID 32967703, 2020). "Furthermore, miR-182 and miR-187 were also differentially expressed according to clinical variables, such as the tumor stage, Gleason score, the status of TMPRSS2-ERG and progression." (PMID 32213205, 2020). "In contrast, the PDE4D5 score was only significantly associated with BCR in TMPRSS2-ERG fusion negative tumours (logrank p<0.0001 vs. logrank p=0.4 for TMPRSS2-ERG+ tumours)." (PMID 31275657, 2019). "We also investigated whether PAX5, SBDS, and TMPRSS2 could be used as biomarkers by evaluating the stability of primary tumor cells grown in 2D or 3D culture media." (PMID 30792990, 2019). "Importantly, we also demonstrated that sGC inhibitor treatment repressed tumor growth in TMPRSS2-ERG-positive PCa xenograft models and can act in synergy with a potent AR antagonist, enzalutamide." (PMID 30718921, 2019). "Each TMPRSS2‐ERG fusion positive tumor presented with minimally two and maximally five TMPRSS2‐ERG fusion isoforms (total of 40 fusion junctions), with three patients also presenting a novel fusion event: RP11‐356O9.1‐ETV1 in two patients and PTPRK‐LAMA2 in a single patient." (PMID 31090091, 2019). "In the present study, we investigated whether genomic TMPRSS2-ERG fusion sequences fulfill the molecular criteria for use as patient individual noninvasive tumor markers." (PMID 31915468, 2019). "Importantly, EIPs reduce proliferation, invasion, and tumor growth of prostate tumors bearing the TMPRSS2-ERG gene fusion." (PMID 31366128, 2019). "The recent study of whole-genome sequences of 57 primary prostate tumors highlighted NKX3-1 and FOXP1 loss, and TMPRSS2–ERG fusion as highly clonal, meaning that these events occur very early in tumor development and are probably important for tumor initiation." (PMID 29734647, 2018). "Consequently, TMPRSS2-ERG fusion was positive in patients with surgical margin invaded by tumor cells." (PMID 30459527, 2018). "Here, we used intracardiac injections to evaluate whether the TMPRSS2-ERG fusion plays a role in tumor propagation to the bone." (PMID 28055969, 2017). "Crucially, this indicates a major involvement of the fusion in bone metastases, and therefore suggests that the TMPRSS2-ERG fusion may play a role in bone tropism of PCa tumor cells." (PMID 28055969, 2017).
tumor (continued). "However, our results indicate that the upregulation of TMPRSS2-ETV gene fusion by E2 enhances the tumor-promoting activities of the NF-κB pathway through induction of growth and metastasis-related genes (cyclin D1 and MMPs)." (PMID 28968951, 2017). "In an effort to characterize our new cell lines and to evaluate whether TMPRSS2-ERG could influence tumor development in an animal model system, we inoculated in PC3M-luc control or TMPRSS2-ERG cells the right flank of male SCID mice." (PMID 28055969, 2017). "In this paper, we used a luciferase expressing cell lines derivatives from PC3M, PC3M-luc-C6 (PC3M-luc), in a mouse model in order to evaluate the consequences of TMPRSS2-ERG fusion on tumor development using dynamic monitoring with bioluminescence imaging (BLI)." (PMID 28055969, 2017). "The influence of TMPRSS2-ERG fusion on subcutaneous tumor growth has already been reported." (PMID 28055969, 2017). "We asked whether Tmprss2-CreERT2 is active in the tumor initiating cells and if Tmprss2-CreERT2-mediated deletion of tumor suppressor genes can generate tissue specific tumorigenesis." (PMID 27536883, 2016). "To test whether the over-expression was due to TMPRSS2:ERG fusions, we conducted allele-specific RT-PCR for 49 paired tumor-normal tissue samples." (PMID 28027300, 2016). "Indeed, when stratified by TMPRSS2-ERG incidence it is clear that PDE4D7 is most significantly upregulated in low-grade TMPRSS2-ERG-positive tumours." (PMID 26575822, 2015). "We did not detect TMPRSS2-ERG gene fusion in this patient, however, we found that TMPRSS2 gene was fused with other partners including ETV4, TRIP4, and PNPO in the visit 1 patient tumor tissue, and all these TMPRSS2 involved fusion events were rediscovered in PDXs." (PMID 26695660, 2015). "The TMPRSS2-ERG gene rearrangement status of patient samples was determined by transformation of the exon array and RNA seq expression data to robust z-scores followed by the application of a threshold >3 to define a positive TMPRSS2-ERG gene fusion event in a tumour sample." (PMID 26575822, 2015). "In addition, we find that in primary TMPRSS2-ERG-positive tumours PDE4D7 expression is significantly positively correlated with low-grade disease and a reduced likelihood of progression after primary treatment." (PMID 26575822, 2015). "Expression of TMPRSS2-ERG fusion shows a striking correlation with AR expression in tumor biopsies." (PMID 25277175, 2014). "Significantly downregulated genes in NHT tumours (DESeq comparison; Benjamini-Hochberg P <0.05) were typically androgen responsive (for example, TMPRSS2, KLK3, BMPR1B, TPD52) or steroidogenesis-related (for example, DHCR24, SCD), consistent with a reduction in androgen receptor activity." (PMID 25155515, 2014). "Different genomic rearrangements and alternative splicing events around the junction region lead to multiple combination of Tmprss2:ERG fusion transcripts that correlate with different tumor aggressiveness, but their specific functions and biological activities are still unclear." (PMID 23472063, 2013). "Nevertheless, in one case, TMPRSS2/ERG-expressing tumor metastasized into the murine lung." (PMID 21747944, 2011). "We further show that CRISP3 is a direct target of overexpressed ERG, suggesting that CRISP3 may be a mediator of tumor progression driven by the TMPRSS2-ERG rearrangement." (PMID 21814574, 2011). "As previously reported, patients with TMPRSS2–ERG fusion-positive tumours had a significantly higher expression of ERG transcripts (P-value 3.48 × 10−11, two-sided Student's t-test), which is most likely a result of androgen-responsive promoter elements in TMPRSS2 driving expression." (PMID 20068566, 2010). "Finally, although not replicated in the Swedish cohort, we found attenuation of the potent tumour-suppressor phosphatase and tensin homologue, PTEN, in TMPRSS2–ERG fusion-positive tumours." (PMID 20068566, 2010).
tumor (continued). "Among the 81 patients who had TMPRSS2:ERG fusion transcripts within their tumour tissue, 37 (45.7%) experienced biochemical recurrence, whereas among the 84 patients who had tumours that lacked fusion, only six (7.1%) experienced a relapse (odds ratio=10.9, 95% CI=4.3–27.9, P=10−7)." (PMID 17971772, 2007). "Furthermore, recently, it was found that the detection of TMPRSS2-ERG fusion in circulating tumor cells of castration-resistant prostate cancer (CRPC) patients may predict resistance to taxanes." (PMID 38674385, 2024). "IHC staining of two representative tumor specimens revealed that a high expression level of TMPRSS2 was accompanied by a high expression level of nuclear AhR and IL18, while a low expression level of TMPRSS2 was associated with a low expression level of nuclear AhR and IL18." (PMID 36975376, 2023). "Therefore, a systematic and in‐depth investigation of the function of TMPRSS2 in multiple tumours and COVID‐19 could pave the way for precision medicine and TMPRSS2‐targeted strategies." (PMID 34951103, 2022). "However, low expression of TMPRSS2 was irrelevant to the prognosis of tumor patients." (PMID 35281819, 2022). "Biomarkers between benign and malignant samples were analyzed using both NMR and LC-MS, with focuses on metabolic profiles that could identify the aggressiveness and progression of disease according to Gleason scores reflecting tumor aggressiveness and gene fusion, TMPRSS2-ERG, of progression." (PMID 35463966, 2022). "The mutation frequency of the TMPRSS2 gene is not high in most tumour types, suggesting that the mutation of the TMPRSS2 gene itself may have little effect on the TMPRSS2 gene function." (PMID 34951103, 2022). "However, the function of TMPRSS2 in the progression of tumors and the relationship between the tumors and tumor immunity remains unknown." (PMID 35558557, 2022). "TMPRSS2-ERG could be involved in epithelial–mesenchymal transition (EMT) during tumor development." (PMID 32694934, 2020). "Therefore, we hypothesized that increased cGMP in TMPRSS2-ERG-positive PCa cells can promote tumor cell proliferation." (PMID 30718921, 2019). "For the highlighted risk regions, we considered mRNA expression analysis of candidate target genes in fusion-positive and negative tumor tissues, to investigate the mechanistic interplay between the somatic TMPRSS2:ERG phenotype and the germline genotype of associated risk variants." (PMID 27798103, 2016). "In addition, FISH on tissue micro arrays may miss TMPRSS2:ERG positive tumor foci, due to the limited area of analyzed tumor tissue, while qPCR on macro-dissected fresh-frozen tumor tissue could enable a more comprehensive evaluation." (PMID 27798103, 2016). "The group found that loss of miR-26a led to upregulation of EZH2 in TMPRSS2:ERG negative tumours." (PMID 25496077, 2014). "Metastatic tumor cells were ERG + in 26% of the cases (36 of 139), suggesting TMPRSS2-ERG fusion gene expression." (PMID 40841830, 2025). "Higher expression levels of TMPRSS2 were found in blood from patients infected with SARS-CoV-2, while TMPRSS2 expression levels significantly varied between the tumor types analyzed." (PMID 40055791, 2025). "ACE2 and TMPRSS2 are the entry points of SARS‐CoV‐2, and their downstream signaling pathways play an important role in the tumor microenvironment." (PMID 40145441, 2025). "The TMPRSS2:ERG fusion leads to the overexpression of the ERG transcription factor, a key driver of tumour invasion and progression." (PMID 40165885, 2025). "TMPRSS2–ERG gene fusion is an important molecular marker of PCa, which can promote tumor cell proliferation and metastasis." (PMID 40145441, 2025). "The ERG+/PTEN+ tumour molecular subtype of PCa is characterised by ERG rearrangements, most commonly the TMPRSS2:ERG fusion, and intact PTEN function." (PMID 40165885, 2025). "The fusion of TMPRSS2 and ETS genes, particularly involving ERG, regulates the AR pathway and impairs tumor proliferation checkpoints." (PMID 40746562, 2025).
tumor (continued). "Despite these challenges, the TMPRSS2:ERG fusion remains a potential therapeutic target due to its specificity to PCa and its overexpression throughout various stages of tumour progression." (PMID 40165885, 2025). "In urine, TMPRSS2-ERG presence correlates with clinically significant PCa, tumour size and a high Gleason score at prostatectomy." (PMID 39329818, 2024). "After correcting tumor purity, the TMPRSS2 mRNA expression level was found to significantly correlate with B-cells, CD8+ T-cells, neutrophils, macrophages, Th1 cells, and Treg in the tumor." (PMID 39057128, 2024). "TMPRSS2::ERG was the most frequent fusion in both cohorts, detected in 45% of FF_RP tumor samples and 28.6% of TCGA_PRAD samples." (PMID 37349736, 2023). "TMPRSS2-ERG fusions are responsible for checkpoint impairment in the cell cycle and for tumor proliferation, but also tumor cell migration and invasiveness by overexpression on metalloproteinase 9 (MMP9) and plexin A2." (PMID 37021836, 2023). "The common to European ERG fusions, including TMPRSS2‐ERG, were significantly under‐represented in African tumours (37.7% vs 13.3%, P = 0.0004), while private ERG (12 vs." (PMID 36629046, 2023). "Integrating above results, we found that the mRNA expression level of TMPRSS2 in LUAD and LUSC tumor tissues is lower than that in the corresponding normal tissues." (PMID 36992839, 2023). "The analysis of tumor suppressors showed that NFIX had a positive correlation with different tumor suppressors, among which TMPRSS2 had the highest correlation coefficient." (PMID 37686043, 2023). "On the contrary, the tumor suppressor NKX3.1 inhibits the juxtaposition mediated by AR of TMPRSS2 and ERG loci and promotes homology-directed repair, thereby disfavoring TMPRSS2-ERG fusion formation." (PMID 35267426, 2022). "In this study, we demonstrated that TMPRSS2 affects the prognosis of LUAD and BRCA through tumor immune cell infiltration, and the biological mechanism of TRPRSS2 needed to be in-depth experimental exploration in the future." (PMID 35558557, 2022). "Current PCa markers such as PSA, PCA3, TMPRSS2-ERG, and PSMA are expressed in PCa cells, but some of them are differently expressed depending on the location even in the same tumor from the same patient, complicating the implementation of a general therapy." (PMID 36008950, 2022). "To better explore the internal connection of TMPRSS2, COVID‐19 and tumour, we exploited GeneMANIA and STRING webserver to predict the functional protein partners of TMPRSS2." (PMID 34951103, 2022). "Even in this case, we identified CNAs in genes potentially related to tumor recurrence, such as TGFB2 and TMPRSS2." (PMID 35841413, 2022). "This one sample (Patient 6, T4) was ERG‐negative on IHC and displayed a relatively low TMPRSS2:ERG signal on RNA‐seq, likely due to contamination with cells from the nearby ERG‐positive tumor focus T3." (PMID 35220606, 2022). "Some recurrent fusions appear to be almost exclusively clonal (CCDC6-RET, BRAF-KIAA1549, and TMPRSS2-ERG), suggesting that gain-of-function SVs occur early during tumor development." (PMID 33831375, 2021). "In some tumor types, especially in gastrointestinal cancers, expression of ACE2 and TMPRSS2 is highly correlated." (PMID 33707526, 2021). "As a result, the androgen-responsive promoter elements of TMPRSS2 drive the expression of the ETS family transcription factors to promote PCa progression, invasion, and tumor aggressiveness, and lead to a significantly reduced survival." (PMID 34502458, 2021). "We next analyzed the levels of ACE2 and TMPRSS2 in normal and tumor tissue by combining the GTEx and TCGA datasets (KIRC: 100 normal and 539 tumor samples; KIRP: 60 normal and 289 tumor samples)." (PMID 34131396, 2021). "Another study investigated the expression of ACE2 and TMPRSS2 genes in LUAD and LUSC and suggested higher and nearly equal ACE2 expression in LUAD and LUSC tumor tissues than in normal tissues, respectively." (PMID 34094930, 2021).